PIK3CA (phosphatidylinositol-4,5-bisphosphate 3-kinase catalytic subunit alpha)
Diseases named in the same sentence as PIK3CA in open-access papers (continued):
Sharing a sentence is not in itself a finding about the gene and the disease.
colon carcinoma (continued). "The mutational frequency of PIK3CA in colon cancers shows gender bias with more frequency in the females as compared to the males." (PMID 31905960, 2019). "The PDX 36M1 was derived from a synchronous liver metastasis of a stage IV colon tumor, and the PDX 40 from a stage IV colon tumor, which presented two activating mutations in PIK3CA and ERBB2 genes." (PMID 31627299, 2019). "PIK3CA mutations were reported to be more prevalent in the “protruded-type” of colon cancer as compared to the “flat-type” colon cancers." (PMID 31905960, 2019). "We found that PIK3CA mutation frequency was also significantly different in the three sub-clusters of colon cancer cells, so we tested the sensitivity of PI3K-mTOR signaling pathway inhibitors in different sub-clusters of colon cancer cells." (PMID 31596728, 2019). "It was also demonstrated that PIK3CA mutations conferred resistance to colon cancer cells against anti-EGFR antibodies." (PMID 31905960, 2019). "KRAS and PIK3CA were the only mutated genes showing differences according to the tumor location, mainly for right colon cancers." (PMID 29632645, 2018). "For stage II–III colon cancer, PIK3CA mutation was significantly associated with tumor recurrence and poor survival." (PMID 29652830, 2018). "In 450 stage I to III colon cancers, PIK3CA mutation was associated with a significant increase in colon cancer–specific mortality in the KRAS wt patients." (PMID 29666387, 2018). "In a study of 450 patients with stage I to III colon cancer, for example, PIK3CA mutations predicted a poorer prognosis, but only among KRAS wild-type CRC patients." (PMID 29666387, 2018). "Our findings indicate that aspirin causes cell cycle arrest, induces apoptosis, and leads to loss of cell viability more profoundly in PIK3CA-mutated colon cancer cells than in PIK3CA-wild-type colon cancer cells." (PMID 29152088, 2017). "Combined, these findings further support the use of PIK3CA mutation status as a biomarker for precision aspirin chemoprevention and adjuvant therapy strategies for colon cancer." (PMID 29152088, 2017). "The present study was designed to detect the potency of aspirin therapy in colon cancer cell lines according to major somatic driver mutations such as PIK3CA, BRAF, and KRAS mutations." (PMID 29152088, 2017). "The significantly greater levels of PIK3CA H1047R mutation in male versus female colonic mucosa are consistent with men having a greater risk of developing colon cancer than women." (PMID 28755461, 2017). "Aspirin treatment led to a more profound induction of apoptosis in colon cancer cells harboring a PIK3CA mutation than in those with wild-type PIK3CA." (PMID 29152088, 2017). "The reduced viability of PIK3CA-mutant colon cancer cells was also confirmed in colon cancer cells containing the heterozygous PIK3CA knock-in mutations c.3140A>G (p.H1047R) and c.1633G>A (p.E545K)." (PMID 29152088, 2017). "Additional important findings from our study include the significantly lower activation of the PI3K/AKT/mTOR pathway in rectal tumors compared to left- and right-sided colon tumors, with lower mutation rates of PIK3CA and PTEN in rectal tumors." (PMID 29156800, 2017). "For example, PIK3CA is the target gene of hsa-mir-363, and a previous study reports high frequency mutations of PIK3CA in colon cancer." (PMID 29513198, 2017). "Tumor specific EGFR downstream signaling mutations in KRAS, BRAF, PTEN, and PIK3CA cause reduced benefit of cetuximab therapy in colon carcinoma patients." (PMID 27100871, 2016). "In the present study, we used HCT-116 colon cancer cell line (K-Ras, PIK3CA mutated) to explore a functional presence of a K+/Ca2+ channel complex and to define the potential role of this channel complex in calcium and EGF–dependent cancer cell migration." (PMID 27102434, 2016). "A mutation of PIK3CA was present in about 20% of patients, and appeared to explain most of the reduction in colon cancer mortality by aspirin." (PMID 27096951, 2016).
colon carcinoma (continued). "Similar percentages of mutations (40-50%) are found in KRAS and BRAF and 17% of PIK3CA mutations have been determined in colon carcinoma patients." (PMID 25885658, 2015). "The authors also observed that ATP-competitive inhibitors of mTOR exhibited anticancer effects on both PIK3CA mutated as well as on PIK3CA wild type colon cancer cells." (PMID 26404261, 2015). "Among RAF/RAS mutant lines, co-occurring PIK3CA/PTEN mutations conferred a cytostatic response instead of a cytotoxic response for colon cancer cells." (PMID 26404261, 2015). "PIK3CA, which encodes the p110α catalytic subunit of PI3Kα, is one of the most frequently altered oncogenes in colon cancer (CC), but its prognostic value is still a matter of debate." (PMID 25641861, 2015). "A recent study showed that NVP-BEZ235 is effective on both PIK3CA-mutated and unmutated colon cancer cell lines." (PMID 25965911, 2015). "We found that the frequencies of BRAF and PIK3CA mutations were significantly lower in rectal than in colon cancer." (PMID 25367198, 2014). "Several genes in the backbone of the CHIEF pathway were associated with survival, including PIK3CA for colon cancer and PRKAG2, STK11, and TSC2 for rectal cancer." (PMID 25541970, 2014). "High expression of nuclear β-Catenin perfectly identified colon cancer cases with synchronous metastasis in cases with PTEN loss or activating PIK3CA mutations only, both indicative of active PI3K signaling." (PMID 24930890, 2014). "(B) High nuclear β-Catenin expression and concurrent activating PIK3CA mutation or loss of PTEN expression correlate with distant metastasis in colon cancer." (PMID 24930890, 2014). "In summary, cPLA2α plays a critical role in regulation of AKT phosphorylation and cell proliferation in colon cancer cells in which PIK3CA has a gain-function mutation." (PMID 25365190, 2014). "In the logistic regression analysis, PIK3CA mutation appeared more frequently in colon cancer than rectum at the same time, which was supported by a recent study." (PMID 24339949, 2013). "Activating mutations of oncogenes such as KRAS, BRAF or PIK3CA that are common to colon cancer have been reported to be associated with resistance to cytotoxic agents or molecularly targeted drugs." (PMID 23852390, 2013). "Several recent reports suggested that aspirin usage improves colon cancer mortalities especially among patients with mutated-PIK3CA, indicating PIK3CA as potential biomarker in colon cancer." (PMID 23863689, 2013). "Residual colon tumor FFPE specimens with BRAF V600E or PIK3CA H1047R mutations were independently diluted in two-fold decrements." (PMID 24001039, 2013). "In our study, we identified a 4% incidence for PIK3CA mutations, which is lower than the 10% to 30% reported in colon cancer." (PMID 23617638, 2013). "Regarding PIK3CA, a large cohort study has recently shown that PIK3CA mutation was associated with poor prognosis among patients with resectable stage I to III colon cancer." (PMID 23617638, 2013). "Furthermore, we introduce the first genetically engineered mouse model (GEMM) that develops colonic tumors progressing to liver metastases within an intact immune system, driven by a single oncogenic mutation, Pik3ca." (PMID 39808497, 2025). "Seven out of the ten patients with PIK3CA mutations had right-sided colon tumors." (PMID 39335120, 2024). "Furthermore, almost all colon cancer-associated PIK3CA mutations were found to elevate lipid kinase activity compared to wild-type p110α." (PMID 38848145, 2024). "When talking about the exact affected biochemical pathways, examples include the notch signalling pathway affected by NOTCH1 mutations in T-ALL, the PI3K-AKT signalling pathway influenced by PIK3CA mutations in breast and colon cancer, and the Wnt/β-catenin pathway in CRC’ and LIHC." (PMID 38542080, 2024).
colon carcinoma (continued). "To assess whether phosphorylation of p110α affects the CRC progression, we endogenously mutated Y317 or Y508 to F (phenylalanine) on PIK3CA locus using CRISPR/Cas9 mediated genome editing strategy in colon cancer cells (HCT116, DLD1, SW480, LoVo)." (PMID 37689735, 2023). "Phosphatidylinositol-4,5-bisphosphate 3-kinase catalytic subunit alpha (PIK3CA), encoding the p110 subunit of class I PI3Ks, is highly activated and mutated in various human cancers, including the brain, liver, stomach, lung, and colon cancers." (PMID 38033642, 2023). "Moreover, the protein levels of P-gp and BCRP were found to be significantly higher in colon cancer tissues with PIK3CA mutations than in PIK3CA WT tissues." (PMID 35619132, 2022). "Thus, P-gp and BCRP expression in colon cancer cells with PIK3CA mutation was detected by Western blotting analysis." (PMID 35619132, 2022). "Consistently, immunohistochemistry staining of human colon cancer specimens showed that p85β was predominantly localized in the nuclei of tumors with a PIK3CA E545K mutation, but mostly localized in the cytoplasm of tumors with wild-type PIK3CA or a PIK3CA H1047R mutation." (PMID 35418124, 2022). "In patients with stage III colon cancer, PIK3CA mutations in the exon 20 have been shown to have a worse outcome, while patients harboring both exon 9 and 20 mutations exhibit a worse prognosis compared to those with PIK3CA wild-type or with PIK3CA mutation in either of the exons." (PMID 30736475, 2019). "To ascertain the effect of MEK inhibition on β-catenin status in PIK3CA mutant colon cancer cells, we used two special colon cancer cell lines: DLD-1–PIK3CA wt (cell line 351), which has the mutant allele knocked out, and DLD-1–PIK3CA mt (cell line 353), which has the wt allele knocked out." (PMID 30944457, 2019). "Likewise, NRAS-Q61K and NRAS-Q61R mutations in skin and blood cancers; PIK3CA-E545K and PIK3CA-H1047R mutations in breast, lung, and colon cancers; and the C-Kit-D816V mutation in blood cancer are reported to commonly and frequently occur." (PMID 30813491, 2019). "To test this hypothesis, we assessed the effect of aspirin treatment on cell cycle arrest and apoptosis using 13 colon cancer cell lines with known PIK3CA mutation status and isogenic colon cancer cells with knock-in PIK3CA-activating mutations." (PMID 29152088, 2017). "The results demonstrate that aspirin may selectively cause G0/G1 cell cycle arrest, induce apoptosis, and inhibit cell growth in human colon cancer cells with PIK3CA mutations in vitro." (PMID 29152088, 2017). "All BRAF and 80.8% PIK3CA mutations were from colon cancer patients." (PMID 25367198, 2014). "Comparable findings were reported in primarily apoptosis resistant colon carcinoma cells (HCT116) harbouring an activating mutation in the PIK3CA gene, which yields a constitutive active form of the catalytic α-subunit of the PI3K (phosphatidylinositide 3-kinase)." (PMID 23852022, 2013). "KRAS, BRAF and PIK3CA mutations are commonly found in colon cancers." (PMID 23617638, 2013). "Also, when stratified by KRAS status, a worse colon cancer-specific mortality associated with a PIK3CA mutation was only found in KRAS wild-type tumors." (PMID 24759962, 2013). "Moreover, while the high frequency of KRAS, BRAF and PIK3CA mutations in colon cancer is well documented, other potentially important mutations have not been profiled with a large number of clinical samples." (PMID 20233444, 2010). "Furthermore, several studies describe that PIK3CA mutations are more often present in right-sided colon tumors, which could explain why this variable lost significance after adjusting for tumor location." (PMID 39286015, 2024).
colon carcinoma (continued). "Furthermore, there are two large ongoing placebo-controlled randomized controlled trials that examine the effect of both aspirin and metformin in stage I-III CRC, and the effect of aspirin in stage III and high-risk stage II colon cancer with PIK3CA mutation, respectively." (PMID 35371873, 2022). "Although our results demonstrated that among left-sided colon cancer patients, those with early recurrence were more likely to carry PIK3CA and NRAS mutations than those with late recurrence, the number of patients was small, and selection bias might have occurred." (PMID 33919924, 2021). "Likewise, most mutations in PIK3CA were from colon cancer patients (21/26, P = 0.014)." (PMID 25367198, 2014). "The histology of the tumors in our model closely resembles the colon adenocarcinoma phenotype observed in patients, providing a more accurate representation of PIK3CA-driven colon cancers." (PMID 39808497, 2025). "LY3023414, a dual PI3K/MTOR inhibitor, decreases cell proliferation in colorectal cancer cells as well as a reducing the growth of PIK3CA-mutant colon tumors in vivo." (PMID 40564038, 2025). "RAS, PIK3CA, and HER2 mutations can commonly co-occur with HER2 amplification, with higher rates in colon cancer than rectal cancer." (PMID 40742050, 2025). "Our findings are distinct from previous results obtained in breast and colonic carcinoma models, which showed an increased dependency on OGDH only in the presence of mutated PIK3CA." (PMID 38483541, 2024). "In this signaling pathway, the oncogene PIK3CA, encoding the p110α catalytic subunit of PI3K, is one of the most commonly mutated genes in colon cancer." (PMID 39334689, 2024). "CXCL5, a neutrophil chemokine, is upregulated in PIK3CA-mutant mouse colon cancer cells through the NF-κB pathway." (PMID 38194275, 2024). "NETs modulate the antitumor effort of the combination of CB-839 and 5-FU in PIK3CA-mutant mouse colon tumors in immune-competent mice." (PMID 38194275, 2024). "A previous study on colon cancer showed that the concurrence of KRAS and PIK3CA mutations in cells induced the potential synergistic hyperactivation of the RAS/ERK and PI3K/AKT pathways, which result in uncontrolled cell proliferation and metastasis." (PMID 35326657, 2022). "Treatment with the PI3K inhibitor LY294002 has been shown to downregulate PIK3CA signaling and inhibit the progression of PIK3CA-mutant colon cancer." (PMID 36238278, 2022). "Colon cancer cells often with an induced PIK3CA mutant were more sensitive to cetuximab in preclinical studies even than PIK3CA wild-type cells." (PMID 35010119, 2022). "The roles of fisetin, 5-fluorouracil or their combination in PIK3CA wild-type and PIK3CA-mutant colon cancer cells were determined." (PMID 36558146, 2022). "In right-sided colon tumors, patients with MAC had fewer PIK3CA mutations and more AKT1 mutations than patients with NMAC." (PMID 33738258, 2021).
colon carcinoma (continued). "The mutation statuses of HCT 116 colon cancer cells are KRAS mutation (p.G13D) and phosphatidylinositol-4,5-bisphosphate 3-kinase catalytic subunit alpha (PIK3CA) mutation (p.H1047R)." (PMID 34360807, 2021). "PIK3CA mutation is associated with poor prognosis among CRC patients and predicts response of colon cancer cells to the cetuximab." (PMID 35860598, 2021). "The statistics have shown that the mutation rates of PIK3CA and PTEN in CRCs are ∼12% and ∼6%, respectively; mutations of PIK3CA are common in exon 9 and exon 20, and mainly occur in colon-cancer patients." (PMID 32665850, 2020). "The m6A methyltransferase inhibitor SAH 75 elevated the expression of AKT1, PTEN, mTOR, and PIK3CA in stomach and colon cancer cell lines." (PMID 32863943, 2020). "The use of PDX with different mutational profiles shows the efficacy of the combination on a colon tumor liver metastasis (PDX 36M1) and on a primary tumor mutated for PIK3CA and ERBB2 genes (PDX 40)." (PMID 31627299, 2019). "In colon cancer-specific DNA mutations have been identified, BRAF, K-ras, N-ras, and PIK3CA mutations." (PMID 31281432, 2019). "To validate this finding, we selected two colon cancer cell lines with different PIK3CA genotypes, SW620, and DLD-1." (PMID 30944457, 2019). "A recent study on Chinese patients showed that among KRAS, BRAF, PIK3CA and NRAS mutations in stage II to III colon cancers (n = 228), only PIK3CA mutations were an independent prognostic biomarker for poor OS among stage III patients." (PMID 29666387, 2018). "Patients with right colon cancer showed more mutated BRAF (39.1% vs. 5.4%), mutated PIK3CA (13% vs. 1.4%), poorly differentiated tumor (17.4% vs. 3.4%), and peritoneal involvement (26.1% vs. 8.8%) than those with left colon and rectal cancer." (PMID 29169325, 2017). "PIK3CA-mutant colon cancer cell lines were considerably more sensitive to the anti-proliferative effects of aspirin than PIK3CA-wild-type cells." (PMID 29152088, 2017). "As our colon cancer cell panel did not include all possible activating alterations in PIK3CA, we were unable to elucidate the potency of aspirin treatment on colon cancer cells with PIK3CA alterations other than the ones examined." (PMID 29152088, 2017). "We measured the anti-proliferative effect of aspirin at physiologic concentrations in seven PIK3CA-mutant and six PIK3CA-wild-type human colon cancer cell lines." (PMID 29152088, 2017). "In this study, we have shown that physiologically attainable concentrations of aspirin can exert stronger anti-cancer effects on PIK3CA-mutant colon cancer cells relative to PIK3CA-wild-type colon cancer cells." (PMID 29152088, 2017). "The present study is the first to show that the isogenic conversion of a PIK3CA-wild-type colon cancer cell into a PIK3CA-mutant cell line is sufficient to promote sensitization to aspirin." (PMID 29152088, 2017). "In that study, eight colon cancer cell lines and engineered HCT116 cells with PIK3CA kinase domain mutant allele knockout were used to assess the effects of aspirin on cell proliferation and cell-cycle distribution." (PMID 29152088, 2017).